ECRG4 (ECRG4 augurin precursor)
Diseases named in the same sentence as ECRG4 in open-access papers (continued):
Sharing a sentence is not in itself a finding about the gene and the disease.
infection (continued). "In order to evaluate why the ECRG4 KO mice were unable to mount an effective early response to infection, we examined the inflammatory milieu of the cutaneous infection at 24 hours." (PMID 39509414, 2024). "We identified altered expression of the neutrophil surface adhesion molecules CD11b and L-selectin in the ECRG4 KO mice, both of which regulate the rate of neutrophil mobilization and recruitment to the site of infection." (PMID 39509414, 2024). "Ecrg4 gene expression was also downregulated after infection in quiescent middle ear mucosa, concomitantly with increased cell proliferation." (PMID 37041625, 2023). "When infection or inflammation occurs, the protease activates and initiates the downregulation of ECRG4 gene expression, which is released from the cell surface in a processed form." (PMID 36910669, 2023). "In recent years, a large amount of literature supports the involvement of ECRG4 in inflammation, injury, and infection." (PMID 36910669, 2023). "Gene array analysis of OM between WT and ECRG4-null mice for genes with a significant interaction across genotype and infection identified 1,277 differentially expressed genes." (PMID 36092940, 2022). "The decrease in ECRG4 mRNA expression was confirmed by a comparison of qPCR data from control versus 48 h after ME NTHi infection." (PMID 36092940, 2022). "Many of the genes differentially regulated in WT versus ECRG4−/− mice are involved in cell replication and/or differentiation, and by 6 h after infection, the expression of the majority of growth regulators substantially increased in the Ecrg4−/− middle ear." (PMID 36092940, 2022). "After infection, the Ecrg4 gene expression is suppressed and the existing protein is almost completely cleaved to release the extracellular domain as the soluble molecule augurin." (PMID 36092940, 2022). "This early decrease in Ecrg4 gene expression, being lowest at 1 day, preceded the maximal increase in epithelial mucosal thickness observed, which peaked at 2 days after NTHi infection." (PMID 36092940, 2022). "And in earlier study, Ecrg4 expression exhibited a strong decrease beginning 6 h after NTHi inoculation of the ME, which recovered to pre-infection levels by 3d." (PMID 36092940, 2022). "We used a well-characterized animal model of infection induced mucosal inflammation and hyperplasia to characterize the effects of Ecrg4 on mucosal cell migration and proliferation during infection." (PMID 23626679, 2013). "Upon experimental ME infection, Ecrg4 gene expression rapidly decreased by over 80%, between 3 to 48 hrs, post infection." (PMID 23626679, 2013). "Ecrg4 staining recovered as mucosal thickness reversed and the infiltrating cells cleared over 5–7 days after infection." (PMID 23626679, 2013). "Whereas the infection of control or ADgfp animals resulted in a >90% decrease in mucosal Ecrg4 gene expression when compared to untreated animals, Ecrg4 mRNA remained high in animals pre-injected with ADEcrg4 in spite of the NTHi infection (25 vs. 15 fold)." (PMID 23626679, 2013). "We report an inverse relationship between expression of the orphan candidate tumor suppressor gene esophageal cancer related gene 4 (Ecrg4), and the mucosal epithelial cell response to infection in the middle ear (ME)." (PMID 23626679, 2013). "Mining a gene expression database generated by Affimetrix genechip analyses of control and infected mucosa of C57BL/6J:CB F1 mice established that mouse Ecrg4 gene expression was altered in the normal epithelial response to infection." (PMID 23626679, 2013). "The observed Ecrg4 down-regulation was confirmed using qPCR at normal (pre-infected) and at 48 hrs post infection of rat MEs." (PMID 23626679, 2013). "This early decrease in Ecrg4 gene expression preceded the maximal increase in epithelial mucosal thickness observed at 48 hrs after NTHi infection (hashed line)." (PMID 23626679, 2013).
infection (continued). "We have shown that the leukocyte protein ECRG4 enhances early neutrophil recruitment to cutaneous wounds and hypothesized that ECRG4 regulates the early host response to infection." (PMID 39509414, 2024). "Given the importance of ECRG4 in regulating early neutrophil recruitment in wound healing and infection in mice, we hypothesized that it also regulates neutrophil recruitment in humans and evaluated its expression in patients with T2DM." (PMID 39509414, 2024). "Previous work had demonstrated a role for ECRG4 in the early recruitment of neutrophils to cutaneous wounds, leading us to hypothesize that ECRG4 may regulate this critical response to infection." (PMID 39509414, 2024). "Given the decreased number of neutrophils recruited to the site of infection, we hypothesized that there may be a decreased production of these proinflammatory mediators in the ECRG4 KO infection." (PMID 39509414, 2024). "At 6 h after infection, the normalized Ecrg4 expression level by stromal cells had decreased slightly, but by day 1, it was down to 86% matching the gene microarray data which indicated maximum regulation of Ecrg4 expression." (PMID 36092940, 2022). "The fact that normal mucosa expresses Ecrg4 constitutively, but that its expression decreases after infection, is consistent with the hypothesis that Ecrg4 serves a sentinel function on the epithelial cell surface and senses the response to inflammation." (PMID 23626679, 2013). "If an epigenetic set point controlling Ecrg4 expression and regulating Ecrg4 activity in normal tissues exists, then the results here suggest that therapeutics targeting Ecrg4 may modulate mucosal epithelial resistance to infection." (PMID 23626679, 2013). "We found that Ecrg4 is constitutively localized to the normal mucosa but that unlike may other genes, Ecrg4 gene expression is rapidly down-regulated after infection." (PMID 23626679, 2013). "To further explore the relationship between Ecrg4 expression and the mucosal epithelium, we analyzed the DNA microarray data for well-characterized epithelial markers and evaluated their expression levels at different times after infection." (PMID 23626679, 2013). "Moreover, preventing the Ecrg4 decrease after infection affected both mucosal epithelial expansion and leukocyte infiltration through the mucosa and into the ME." (PMID 23626679, 2013). "Over-expression of Ecrg4 in vivo, by pre-injecting MEs with ADEcrg4 48 hrs prior to infection, prevented the natural down-regulation of Ecrg4, reduced mucosal proliferation and prevented inflammatory cell infiltration normally observed after infection." (PMID 23626679, 2013). "Taken together, these data coupled with our current observation in the reduction of inflammatory cell infiltration of the ME cavity again support the hypothesis that Ecrg4 participates in the inflammatory cascade that follows infection." (PMID 23626679, 2013). "To test this hypothesis, we used a transduction strategy utilized to explore the possibility that the natural inhibition of Ecrg4 expression after infection was related to the hyperplasia of epithelial mucosa." (PMID 23626679, 2013). "If so, the findings reported here would suggest that the capacity of gene expression to restore Ecrg4 protein onto the cell surface might define the extent and length of the inflammatory response to infection." (PMID 23626679, 2013). "These experiments demonstrate that ECRG4 can regulate the expression of key neutrophil surface adhesion receptors responsible for mediating neutrophil mobilization from the BM, tethering, and rolling along the endothelium and ultimate migration to the site of injury or infection." (PMID 39509414, 2024). "Using an intradermal MRSA infection model with the community acquired strain USA300 LAC, we evaluated the response of ECRG4 KO mice to cutaneous infection." (PMID 39509414, 2024).
infection (continued). "The many immune-related genes down-regulated by lack of ECRG4, especially at 6 h after infection, also indicate a major role in regulating immunity." (PMID 36092940, 2022).
bacterial infection (1 paper, 2013). "To investigate the role of Ecrg4 in mucosal epithelia, we turned to a well-described model of mucosal epithelial inflammation that is generated by bacterial infection of the ME." (PMID 23626679, 2013).
ECRG4 also shares sentences with these, for which no sentence is quoted: nasopharyngeal carcinoma (4 papers); lung carcinoma (2); renal cell carcinoma (2); abscess (1); anaplastic astrocytoma (1); Arrhythmia (1); breast tumors (1); chondrosarcoma (1); choroid plexus papilloma (1); colorectal tumors (1); dementia (1); epilepsy (1); fibrosarcoma (1); head and neck squamous cell carcinoma (1); Hyperglycemia (1); Hyperoxaluria (1); invasive ductal breast carcinoma (1); kidney cancer (1); kidney diseases (1); leukemia (1); lymph node metastasis (1); malignant glioma (1); non-small cell lung carcinoma (1); oral squamous cell carcinoma (1); papillary thyroid carcinoma (1); prostate (1); rectal cancer (1); Renal insufficiency (1); squamous cell carcinoma of the (1); status epilepticus (1).